HDAC1 (histone deacetylase 1)
Diseases named in the same sentence as HDAC1 in open-access papers (continued):
Sharing a sentence is not in itself a finding about the gene and the disease.
glioblastoma (31 papers, 2012 to 2026). The most malignant astrocytic tumor (WHO grade IV). "In addition, has been suggested that increased activation of HDAC1/2/6 and Sp1 underlies therapeutic resistance and tumor growth in glioblastoma." (PMID 35545840, 2022). "HDAC-1 overexpression has been significantly associated with glioblastoma (HG by definition) and poorly differentiated mobile tongue SCC, lip SCC, non-small cell lung (NSCLC), hepatocellular, prostate, serous subtype of endometrial and ovarian and urothelial bladder carcinoma." (PMID 33799478, 2021). "In glioblastoma cells, histone deacetylase 1/2 (HDAC-1/2) can contribute to the Warburg effect through the c-Myc pathway." (PMID 40696413, 2025). "A recent study in glioblastoma demonstrated that the HDAC1/2/6/SP1 pathway promoted therapeutic resistance by upregulating DNA repair pathways." (PMID 39800760, 2025). "Recent studies have shown that TOPK can regulate the activity of HDAC1, while HDAC1 can activate NF-κB and lead to the malignant phenotype of glioblastoma." (PMID 35756488, 2022). "It has been reported that NFATc1 serves as a regulator of the transcriptional activity of histone deacetylase 1 (HDAC1) in its management of glioblastoma." (PMID 36092961, 2022). "As treatment options for recurrent glioblastomas remain scarce, we address the role of HDAC1/2/3 in TMZ-resistance." (PMID 35365623, 2022). "Here, we showed that the combined inhibition of TRAP1 by gamitrinib and histone deacetylases (HDAC1/HDAC2) through romidepsin or panobinostat caused synergistic growth reduction of established and patient-derived xenograft (PDX) glioblastoma cells." (PMID 32664214, 2020). "Taken together, we have provided evidence that simultaneous targeting of TRAP1 and HDAC1/2 is efficacious to reduce tumor growth in model systems of glioblastoma." (PMID 32664214, 2020). "To investigate the role of HDAC1 knockdown on the growth of glioblastoma cell lines, we performed CCK-8 assay to examine the proliferation of U251 and T98G cells." (PMID 28624794, 2017). "To validate the GSEA analysis of HDAC1, we analyzed the mRNA and protein levels of the apoptosis and invasion pathway-related factors in HDAC1-shRNA-infected glioblastoma cells." (PMID 28624794, 2017). "Taken together, these data suggest an anti-proliferative and pro-apoptotic role of HDAC1-shRNA in glioblastoma cells." (PMID 28624794, 2017). "Consistent with a previous study, our data showed that HDAC1 knockdown not only inhibited cell proliferation, migration, adhesion, and invasion in glioblastoma cell lines but also induced apoptosis and inhibited tumor growth in vivo." (PMID 28624794, 2017). "In particular, HDAC1 increases the expression of anti-inflammatory cytokines in inflammatory diseases of the oral cavity and glioblastoma, HDAC1 and HDAC3 are hyperexpressed in cardiomyocytes in cardiomyopathy, and HDAC2 regulates the activation of hepatic stellate cells in biliary atresia." (PMID 40943548, 2025). "Furthermore, five histone acetylation regulators were selected to be considered as the significant glioblastoma prognosis genes, in which HDAC1, HDAC3, HDAC4 and HDAC7 belong to histone deacetylases differently, HAT1 is a histone acetylase." (PMID 39068393, 2024). "In addition, it has been suggested that increased activation of HDAC1/2/6 and Sp1 is the basis of glioblastoma drug resistance and tumor growth." (PMID 36227941, 2022). "Glioblastoma significantly overexpresses the class I HDACs HDAC1/3/8." (PMID 35365623, 2022). "Therefore, a comprehensive effect of HDAC1 downregulation on glioblastoma cell invasion needs further investigation." (PMID 28624794, 2017). "Our results suggest a role of HDAC1 in the promotion of glioblastoma invasion." (PMID 28624794, 2017).
glioblastoma (continued). "We observed that the expression of apoptosis-related factors (BIM, BAX and cleaved CASPASE3) and an invasion-related factor (E-CADHERIN) were higher, while the expression of related invasion factors (TWIST1, SNAIL and MMP9) were lower in glioblastoma cells with HDAC1-shRNA infection." (PMID 28624794, 2017). "Although knockdown of HDAC1 inhibited the cell invasion of glioblastoma, it may, in part, due to the inhibition of cell proliferation of glioblastoma." (PMID 28624794, 2017). "Specifically, HDAC1 is highly expressed in glioblastoma (GBM) tissues, where it promotes the invasion and migration of GBM cells by regulating the epithelial-mesenchymal transition (EMT) process." (PMID 39620228, 2024). "This study investigates the effects of Paromomycin on SUMOylation-related pathways in glioblastoma (GBM), specifically targeting HDAC1 inhibition." (PMID 39723246, 2024). "Other studies have shown that saffron extracts decrease HDAC1 and HDAC3 expression in glioblastoma cell lines under treatment with saffron extracts in a dose-dependent manner." (PMID 38201944, 2023). "It is indicated that HDAC4 has a better prognosis, while, accordingly, HAT1, HDAC1, HDAC3 and HDAC7 may have a poor prognosis for glioblastoma." (PMID 39068393, 2024). "In addition to the expression changes of SLC30A3 by metal ion stimulation, HDAC1 overexpressed in glioblastoma inhibits the expression of SLC30A3 by deacetylation modification, which is related to the malignant phenotype of glioblastoma." (PMID 38533032, 2024). "A screen on survival-related genes for glioblastoma conducted on a dataset downloaded from the GEO database revealed that HDAC1 and PDIA3 were highly expressed in GBM tissues." (PMID 37686085, 2023). "Glioblastoma (GBM) is the most common and aggressive intracranial malignant brain tumor, and the abnormal expression of HDAC1 is closely correlated to the progression, recurrence and metastasis of GBM cells, making selective inhibition of HDAC1 a promising strategy for GBM treatments." (PMID 32219100, 2020). "As an inhibitor of HDAC1 and HDAC2, SAHA, also known as Vorinostat, has a broad spectrum of epigenetic activities through the inhibition of histone acetylation and has been used to treat several diseases including glioblastoma and non-small-cell lung carcinoma." (PMID 30453545, 2018).
liver cancer (30 papers, 2012 to 2026). An epithelial or non-epithelial malignant neoplasm that arises from the liver. "The fact that the suppression of HDAC1 caused regression of liver cancer cell growth implies that HDAC1 is involved in the regulation of the cell cycle progression." (PMID 22496786, 2012). "Immunoblot analysis of HDAC1 in a subset of human HCC tissues and liver cancer cell lines demonstrated overexpression of HDAC1 in HCCs, and targeted-disruptions of HDAC1 caused growth retardation in various HCC cell lines." (PMID 22496786, 2012). "Moreover, we have recently found that human de-ph-Ser190-C/EBPα (human S190 is an analog of mouse S193 and de-phosphorylation on this residue mimics the S193A mutation) forms complexes with HDAC1, and that these C/EBPα-HDAC1complexes down-regulate hepatocyte specific genes in liver cancer." (PMID 37967813, 2024). "We next analyzed the HDAC1-Sp5 pathway and neuronal pathways in a fresh biobank of pediatric liver cancer samples, including HBL, HCC, and HCN-NOS (n = 36)." (PMID 39001363, 2024). "This manuscript describes a study of the HDAC1-dependent liver cancer pathways in a metastatic microenvironment of pediatric liver cancers." (PMID 39001363, 2024). "Our work shows that the metastatic microenvironment of pediatric liver cancers consists of CAFs and neuron-like cells which are under control of HDAC1-Sp5 axis." (PMID 39001363, 2024). "Prior to the awareness of the expression of the fusion kinase in pediatric liver cancers, we had been working with the role of the HDAC1-Sp5 pathway in generated hbl and hcc/hcn-nos cell lines by inhibiting HDAC." (PMID 39796711, 2024). "Given the elevation of the HDAC1-Sp5 pathway seen in patients with pediatric liver cancers, we have utilized a recently established protocol for generating cell lines with metastatic activities and have established new cell lines from these patients." (PMID 39001363, 2024). "Using oleanolic acid-related liver cancer sequencing data, we found that oleanolic acid decreased the expression of HDAC1 and HDAC2 and increased the expression of HMOX1 and HMOX2." (PMID 38127054, 2023). "The risk score calculated by the expression value of HDAC1, HDAC2, HDAC4, HDAC11, HAT1, and SIRT6 was an independent risk factor for liver cancer." (PMID 36124029, 2022). "Previous research has demonstrated that HOXA10 can promote cancer cell proliferation by directly binding to the HDAC1 promoter and upregulating HDAC1 expression in liver cancer cells." (PMID 33596966, 2021). "Meanwhile, PFDNs also were identified as interacting partners with histone deacetylase 1 protein complexes in liver cancer." (PMID 31957800, 2020). "In liver cancer, targeted disruption of HDAC1 leads to strong anti-proliferative effect and induces autophagic cell death." (PMID 23866964, 2013). "Our data showed that HDAC1 suppresses both cell cycle arrest and caspase-independent autophagic cell death in liver cancer cells." (PMID 22496786, 2012). "In this study, we demonstrated overexpression of HDAC1 in a subset of human HCCs and liver cancer cell lines." (PMID 22496786, 2012). "Interestingly, the upregulation of the histone deacetylases 1 and 3 (HDAC1/3) promotes the overexpression of CNOT1 in hepatic cancer cells." (PMID 39941720, 2025). "In this paper, the HDAC1-Sp5-p21 pathway was investigated to understand its involvement in the generation of metastasis-initiating microenvironments of pediatric liver cancers, and if the inhibition of this pathway together with cisplatin is effective in the elimination of cancer cells." (PMID 39001363, 2024). "Functional genes, e.g., Akt1, Shc1, Prkce, Jun, and Hdac1, were highly related to each other and might play important regulatory roles in the accelerated liver cancer initiation in Zbtb7bΔli livers." (PMID 38225233, 2024).
liver cancer (continued). "For example, HDAC1 is closely related to the prognosis of patients with liver cancer according to the results of the multivariate Cox regression analysis, but a report describing the mechanism by which it promotes tumor occurrence and tumor development has not been published." (PMID 34803509, 2021). "HDAC1 promotes liver cancer metastasis via the FAM99A-miR92a signaling pathway." (PMID 33750478, 2021). "Additionally, the score for patients with HDAC8 expression in liver cancer is notably lower (9%) compared to other members—HDAC1: 90%, HDAC2: 75% and HDAC3: 50%." (PMID 30691229, 2019). "In this study, we found that these cells express high levels of HDAC1; therefore, we examined if histone deacetylase inhibition improves cisplatin anti-proliferative effects and reduces the formation of tumor clusters in pediatric liver cancer metastatic microenvironments." (PMID 39001363, 2024). "Using sequencing data related to liver cancer and cirrhosis, we found that HDAC1 and HDAC2 expression was elevated in liver cancer and cirrhosis, and HMOX1 and HMOX2 expression was decreased." (PMID 38127054, 2023). "This suggest that HDAC1 and HMOX1 are important targets of oleanolic acid for liver cancer inhibition." (PMID 38127054, 2023). "In liver cancer, PROX1 can increase the stability of the transcription factor hypoxia-inducible factor 1α (HIF1α) by recruiting histone deacetylase (HDAC1), leading to EMT of liver cancer cells." (PMID 35342346, 2022). "The expression of ATIC, HDAC1, RHEB, SPNS1 and TMEM74 in liver cancer tissues was significantly higher than that in normal liver tissues." (PMID 34803509, 2021). "Characterization of liver cancer pathways in tumor samples: We generated cell lines from HBL, HCC, HCN-NOS, and lung metastases patient tumors, which were resistant to cisplatin treatments and demonstrated elevated HDAC1 and Sp5 proteins." (PMID 39001363, 2024). "In liver cancer, we identified that the main target of oleanolic acid is HMOX1 and HDAC1." (PMID 38127054, 2023). "We speculate that the activity of HDAC1 and HDAC3 may be related to other phenotypes of liver cancer." (PMID 33718133, 2021). "We found that NEO1 was positively regulated by HDAC1, 2, and YY1, whereas was negatively regulated by HDAC6 in LIHC, suggesting that NEO1 may play an important role in the proliferation and apoptosis of liver cancer cells." (PMID 41407823, 2025). "The upregulation of HDAC1 and HDAC2 suppresses the expression of a key metabolic enzyme in glucose metabolism, fructose-1, 6-bisphosphatase (FBP1), with concomitant increase in lactate production in liver cancer cells, and restoration of FBP1 expression via inhibition of HDAC1/2." (PMID 33255318, 2020). "Interestingly, unlike previous studies demonstrating the increase of apoptosis by HDAC1 inhibition, our results indicated that HDAC1 inactivation did not induce apoptosis in liver cancer." (PMID 22496786, 2012).
leukemia (29 papers, 2007 to 2026). A malignant (clonal) hematologic disorder, involving hematopoietic stem cells and characterized by the presence of primitive or atypical myeloid or lymphoid cells in the bone marrow and the blood. "Previous study indicated that aberrant expression of HDAC1 appears common in tumors including leukemia and is associated with enhanced proliferation and defect in autophagy." (PMID 26649226, 2015). "The aberrant recruitment of HDAC1 is linked to various types of leukemia." (PMID 33187090, 2020). "We performed mass spectrometry to determine if HDAC1 activity influences the recruitment of proteins to the RUNX1 complex in leukemia cells." (PMID 41214140, 2026). "Five independent mouse CM+ leukemia samples were treated with 1 μM entinostat, an HDAC1 inhibitor, or DMSO for 24 h, nuclear lysates prepared, RUNX1 immunoprecipitated, and the precipitate analyzed by mass spectrometry." (PMID 41214140, 2026). "Our lab previously showed that HDAC1 is required for active transcription of RUNX1 target genes in a mouse model of CBFβ::SMMHC (CM) driven AML, making leukemia cells particularly sensitive to the HDAC1 inhibitor, entinostat." (PMID 41214140, 2026). "Previous work from our lab showed that HDAC1 is required for active transcription of a subset of RUNX1 target genes in leukemia cells." (PMID 41214140, 2026). "Class I nuclear HDACs play a significant role in leukemia by functioning as components of repressor complexes such as CoREST, Sin3, MiDAC, and NuRD, all of which include HDAC1/2." (PMID 40284412, 2025). "The same experiment performed using the leukemia cell line MV4-11 validated HDAC1 (Kdapp = 16 μM), HDAC2 (Kdapp = 14 μM), and HDAC6 (Kdapp = 21 μM) and identified HDAC3 (Kdapp = 13 μM) and HDAC10 (Kdapp = 5 μM) as additional targets of (R/S)-LM." (PMID 37322067, 2023). "HDAC1 increases activity of leukemia/lymphoma-related factors and suppresses COMP transcription in C3H10T1/2 cells." (PMID 37681413, 2023). "In previous studies, 8a, as an inhibitor of HDAC1 and Topo I, showed the most significant antiproliferative activity against leukemia cells." (PMID 34073721, 2021). "In brief, we investigated the functional contribution of HDAC‐1/8 in anti‐leukemia effects, especially in CBF‐AML, and evaluated the efficacy of Baicalein in AML cells‐bearing mice model." (PMID 32898337, 2020). "The authors found that in vivo treatment with the HDAC1 inhibitor induced differentiation and apoptosis of leukemia cells, indicating HDAC1 as a potential therapeutic target." (PMID 31817911, 2019). "From our previous study, we demonstrated that the wild fruiting bodies of AC induced cellular apoptosis through HDAC1 hypoacetylation in leukemia HL60 cells." (PMID 30769922, 2019). "Modulation of Klf4 levels by altering shRNA or using an ectopic expression vector can mimic the effects of HDAC1 on cell proliferation, cell cycle, and the expression level of p21 and p27 in human leukemia cell lines K562, HL-60, and U937." (PMID 25341045, 2014). "Excitingly, both analyses of overall and disease-free survival functions indicated that human leukemia patients with lower levels of HDAC1 expression had better follow-up results than those with higher levels of HDAC1 expression." (PMID 25341045, 2014). "To further investigate the function and mechanism of HDAC1 and Klf4 in leukemia cells, we performed tumorigenesis experiments in BLAB/c nude mice." (PMID 25341045, 2014). "Further, knockdown of HDAC1 in leukemia cells K562, HL-60, and U937 significantly increased Klf4 expression and inhibited cell cycle progression and cell proliferation, similar results were found for HDAC inhibitors (VPA and mocetinostat)." (PMID 25341045, 2014). "To illustrate the exact function of HDAC1 in human leukemia, we first modulated the expression level of HDAC1 in the human leukemia cell lines K562, HL-60, and U937." (PMID 25341045, 2014).